RNU6-801P (RNA, U6 small nuclear 801, pseudogene)
Gene: Small nuclear RNA gene on chromosome 6 (19,642,425 to 19,642,529, reverse strand). Ensembl gene ENSG00000200957.
Homologues: Orthologues: chimpanzee U6 (100% identical), macaque U6 (92% identical), guinea pig U6 (81% identical), mouse Gm26375 (80% identical), mouse Gm26500 (78% identical), rat LOC120097964 (72% identical), rabbit U6 (71% identical), pig U6 (70% identical), mouse Gm55611 (69% identical). Paralogues in human: RNU6-1145P (89% identical), RNU6-1316P (89% identical), RNU6-38P (88% identical), RNU6-188P (87% identical), RNU6-20P (87% identical), RNU6-393P (87% identical), RNU6-434P (87% identical), RNU6-477P (87% identical), RNU6-1214P (86% identical), RNU6-1323P (86% identical), RNU6-144P (86% identical), RNU6-181P (86% identical), and 1287 more.